KRTAP10-12 (keratin associated protein 10-12)
Description:
In the hair cortex, hair keratin intermediate filaments are embedded in an interfilamentous matrix, consisting of hair keratin-associated proteins (KRTAP), which are essential for the formation of a rigid and resistant hair shaft through their extensive disulfide bond cross-linking with abundant cysteine residues of hair keratins. The matrix proteins include the high-sulfur and high-glycine-tyrosine keratins.
Synonyms: KAP10.12; KRTAP18-12; KRTAP18.12
Tractability: No criterion of Open Targets' tractability assessment is met for any kind of drug.
Gene: Protein-coding gene on chromosome 21 (44,697,172 to 44,698,044, forward strand). Ensembl gene ENSG00000189169.
Pathways (Reactome):
Developmental Biology: Keratinization
Gene Ontology:
Cellular component: cytosol; keratin filament
Genetic constraint (gnomAD): Loss-of-function variants: 1 observed, 0.68 expected, observed/expected ratio (o/e) 1.47, 90% interval 0.31 to 1.92. That is too few expected variants to judge how well the gene tolerates losing a copy. Missense variants: 311 observed, 329.72 expected, observed/expected ratio (o/e) 0.94, 90% interval 0.86 to 1.04. Synonymous variants: 142 observed, 139.64 expected, observed/expected ratio (o/e) 1.02, 90% interval 0.89 to 1.17.
Homologues: Paralogues in human: KRTAP10-4 (86% identical), KRTAP10-7 (84% identical), KRTAP10-9 (81% identical), KRTAP10-6 (80% identical), KRTAP10-11 (78% identical), KRTAP10-8 (76% identical), KRTAP10-5 (75% identical), KRTAP10-10 (70% identical), KRTAP10-2 (69% identical), KRTAP10-1 (68% identical), KRTAP10-3 (67% identical), KRTAP16-1 (39% identical), and 35 more.